TOPAZ1 (testis and ovary specific TOPAZ 1)
Description:
Important for normal spermatogenesis and male fertility. Specifically required for progression to the post-meiotic stages of spermatocyte development. Seems to be necessary for normal expression levels of a number of testis-expressed gene transcripts, although its role in this process is unclear.
Synonyms: C3orf77; FLJ36157
Tractability: No criterion of Open Targets' tractability assessment is met for any kind of drug.
Gene: Protein-coding gene on chromosome 3 (44,241,886 to 44,332,098, forward strand). Ensembl gene ENSG00000173769.
Subcellular location: Cytoplasm, cytosol
Subcellular location (Human Protein Atlas): Acrosome; Mid piece
Gene Ontology:
Biological process: spermatocyte division
Cellular component: cytosol
Genetic constraint (gnomAD): Loss-of-function variants: 46 observed, 107.56 expected, observed/expected ratio (o/e) 0.43, 90% interval 0.34 to 0.55. The upper end of that interval is the gene's LOEUF score, 0.55, which puts it in group 2 of 6, group 1 being the genes least tolerant of losing a copy. Missense variants: 1,447 observed, 1,570.3 expected, observed/expected ratio (o/e) 0.92, 90% interval 0.88 to 0.96. Synonymous variants: 551 observed, 559.53 expected, observed/expected ratio (o/e) 0.98, 90% interval 0.92 to 1.06.
Homologues: Orthologues: chimpanzee TOPAZ1 (99% identical), macaque TOPAZ1 (95% identical), pig TOPAZ1 (74% identical), rabbit TOPAZ1 (72% identical), rat Topaz1 (66% identical), mouse Topaz1 (66% identical), guinea pig TOPAZ1 (64% identical), tropical clawed frog cyp3a5 (32% identical), zebrafish topaz1 (18% identical).
Diseases named in the same sentence as TOPAZ1 in open-access papers:
TOPAZ1 is named in the same sentence as 5 diseases in open-access papers, as found by Europe PMC text mining. Sharing a sentence is not in itself a finding about the gene and the disease. The quoted sentences say what the papers report.
male infertility (2 papers, 2020 to 2025). The inability of the male to effect fertilization of an ovum after a specified period of unprotected intercourse. "Among them, genes co-location with lncRNA Dnah8 and lncRNA Topaz1 were associated with male infertility." (PMID 40577378, 2025).
Azoospermia (1 paper, 2021). Absence of any measurable level of sperm,whereby spermatozoa cannot be observed even after centrifugation of the semen pellet. "The suppression of Topaz1 in mice (Topaz1–/–) results in azoospermia." (PMID 34277642, 2021).
biliary tract cancer (1 paper, 2023). "While TOPAZ-1 may indicate a role for immunotherapy in the treatment of advanced biliary tract cancers, the data is limited for these other rare cancers." (PMID 37365284, 2023).
TOPAZ1 also shares sentences with these, for which no sentence is quoted: cancer (3 papers); tumor (1).